PRF1 (perforin 1)
Diseases named in the same sentence as PRF1 in open-access papers (continued):
Sharing a sentence is not in itself a finding about the gene and the disease.
tumor (continued). "Nevertheless, deletion of PRF1 decreases the sensitivity of tumor cells to the immune system, thereby facilitating their escape to cytotoxic T lymphocytes (CTLs)." (PMID 39199299, 2024). "The analysis revealed that the expression of T-cell effectors, including FasL, GZMB, PRF1, and IFNγ, was remarkably repressed in the tumor microenvironment." (PMID 39201460, 2024). "In a PRF1‐deficient mouse model, c‐FLIP overexpression prevented tumor cells from being lysed by NK cells in vivo, emphasizing the significance of this protein's function in malignancy." (PMID 38882209, 2024). "To examine the lytic activity of immune T cells in relation to the 3 metabolic subtypes, we used the average expression levels of GZMA and PRF1 to determine the level of lytic activity exhibited by immune T cells in each patient's tumor." (PMID 36860731, 2023). "Tumor killing was reduced when using IFN-γ−/− or Prf1−/− CAR4 T cells, confirming the involvement of both pathways." (PMID 37248395, 2023). "When ctDNA detection was combined with the level of tumour mutational burden (TMB) and a tumour-derived interferon signature (including HLA-DRA, CXCL9/10/11, GZMA, PRF1, CCR5, IFNG, IDO1 and STAT1), the predictive value of the combined score was enhanced." (PMID 38201222, 2023). "The results showed tumor-specific mutations such as missense mutation in exon 9 of PIK3CA P. e542k and germline genes mutations of PRF1, SBDS, and a tumor mutation burden of 12.89 mutations/Mb." (PMID 36930086, 2023). "Although CD8 T cells have been proven to be major contributors of tumor clearance following ICB treatment, GZMA and PRF1 expression in MSI-H tumors was also associated with high levels of activated memory CD4+ T cells, γδ T cells and macrophages." (PMID 37492581, 2023). "One of the main methods by which NK cells destroy tumor cells is by producing cytotoxic granules containing perforin (PRF1) and GzmB." (PMID 36816977, 2023). "We also found that several key cytotoxic genes (such as NKG7, GNLY, PRF1) were more highly expressed in the non-tumor regions." (PMID 38123589, 2023). "By examining the levels of effector molecules (CD69, CD107a, GZMA, IFN-γ, TNF-α, GZMB, and Perforin-1), we also noticed that the tumor-infiltrating CD8+ T cell effector response was significantly enhanced by Rig-I deficiency." (PMID 36927693, 2023). "We found that PRF1 (Perforin 1) was significantly differentially expressed in most cancer types, and PRF1 was highly accurate as a single factor in predicting tumor prognosis in various cancers in the TCGA cohort." (PMID 37291495, 2023). "The lower contribution of the perforin pathway (over the IFN-γ pathway) to tumor killing by CAR4 T cells was also reflected by the fact Prf1−/− CAR4 T cells displayed similar therapeutic benefit as compared to WT CAR4 T cells." (PMID 37248395, 2023). "This suggests that PRF1 mediates tumor-infiltrating T lymphocytes (TIL) oligoclonal amplification-enhanced Th1 (helper T cell type I)-skewed cellular immunity during nivolumab treatment." (PMID 35957907, 2022). "RvD high tumors proved increased gene expression levels of anti-tumor effectors, including GZMA, GZMB, PRF1, and cytolytic score, suggesting higher cytotoxic activity in the tumor microenvironment." (PMID 35742918, 2022). "The results showed that the composition of T status, tumor stage, and clinical grade were significantly distinct between different PRF1 expression groups." (PMID 36097539, 2022). "It has been reported that IFN-γ-related gene expression contributes to immunotherapy prediction, such as CCR5, CXCL9, IFNG, STAT1, and PRF1, and these genes are related to tumor antigen presentation, T cytotoxic activity, and immune cell infiltration." (PMID 35432443, 2022). "Next, to validate activation of the CD8+ T and NK cells, gene expression analysis of GZMa (granzyme a), GZMb (granzyme b) and Prf1 (perforins) showed a significant increase in tumours of mice treated with RGD4C.TPA.IL15IgK particles." (PMID 35758207, 2022).
tumor (continued). "As another role of PRF1 in anti-tumor immune response, PRF1 also maintains the expression of granzyme B in cytotoxic cells." (PMID 35163049, 2022). "This group not only confirmed this expression but also found that this GzmB and Prf-1 secretion is essential for tumor growth." (PMID 35326588, 2022). "TIMER database analysis confirmed that CTSV and MKI67 were highly expressed in tumour tissues, while CXCL8 and PRF1 were expressed at low levels in tumour tissues, which was consistent with our findings." (PMID 35902905, 2022). "We also found that LAIT upregulated the expression of tumour killing molecules Prf1, Gzmb, Ifng, Tnf, and Tnfsf10 (TRAIL) in exhausted and effector memory CD8+ and CD4+ T cells." (PMID 35808806, 2022). "It has been reported that GZMB and PRF1 are highly expressed in tumour tissues, and it was found that tumour tissues with high expression of GZMB and PRF1 have higher infiltration of CD8+ T cells and better tumour prognosis." (PMID 35473583, 2022). "Bulk RNA-seq analysis of sorted tumour-infiltrating CD8+ T cells revealed higher expression of IFNG, GZMB and PRF1 in post-treatment samples, indicating enhanced cytotoxic potential of tumour-infiltrating CD8+ T cells following PI3Kδi treatment." (PMID 35508656, 2022). "The response occurs when cytotoxic T lymphocytes that are cytotoxic to tumor cells proliferate, killing the tumor cells under the action of perforin-1, interferon-γ (IFN-γ), and granulocyte enzymes." (PMID 36466838, 2022). "As a clear marker of the killing ability of immune cells, PRF1 is involved in the establishment of immune homeostasis, pathogen clearance, and tumor monitoring." (PMID 36199375, 2022). "The expression of PRF1 has been used to assess tumor-infiltrating lymphocytes in the tumor microenvironment and was related to the response of patients treated with anti-CTLA-4 therapy and anti-PD-1/PD-L1 therapy." (PMID 36097539, 2022). "For example, IFNG and genes encoding cytolytic enzymes (GZMA, GZMB and PRF1) were relatively up-regulated in SCLC-I tumors, indicating that SCLC-I tumors are characterized by a high level of tumor-infiltrating lymphocytes with potential cytolytic activity." (PMID 36428693, 2022). "The immune surveillance is responsible for infections and is currently found to potentially eradicate tumors: CD8+ T cells recognize tumor cells and secrete granzyme B (GZMB) and perforin (Prf1) to elicit tumor cell apoptosis and death." (PMID 34685495, 2021). "Our data show that c-Rel plays a cell intrinsic role in regulating human and murine NK cell anti-tumor cytotoxicity by regulating the expression of cytotoxic molecules prf1 and gzmb." (PMID 33995369, 2021). "This study revealed that healthy CD8+ T cells expressed hydrolytic GZMB and PRF1 when co-cultured with A549 and significantly suppressed A549-induced tumor growth in vivo." (PMID 34680466, 2021). "GZMB, PRF1 and IFNγ are activation markers and PD-1 is the exhaustion marker of CD8+ T cells, whereas GZMB and PRF1 are major hydrolytic enzymes leading to tumor apoptosis." (PMID 34680466, 2021). "Following recognition and target engagement, NK cells kill target cells mainly via the prf1 and gzmb lysis pathway, but also through ligands that bind to death receptors in tumor cells such as fasL." (PMID 33995369, 2021). "Concurrently, we observed increased expression of genes associated with tumor infiltrating lymphocyte (TIL) cytotoxicity (CD3G, SAP, PRF1, GZMM and GZMK)." (PMID 34084172, 2021). "The CYT score was defined as the average expression level of two CYT marker genes (GZMA and PRF1) in the tumor." (PMID 34616736, 2021). "This was seen in conjunction with upregulation of genes associated with tumor-infiltrating lymphocyte (TIL) cytotoxicity (CD3G, SAP, PRF1, GZMM and GZMK)." (PMID 34084172, 2021).
tumor (continued). "Of note, we focused on three strongly positively related genes in TCGA and METABRIC datasets, including GZMA, IFNG, and PRF1, which played a crucial role in anti-tumor immune of T lymphocytes." (PMID 33407498, 2021). "This is particularly relevant in ACT models, where loss of both perforin-1-mediated killing and sensitivity to IFN-γ resulted in significantly reduced tumor control." (PMID 31924474, 2020). "Given the largely proven vital role of PRF1 in NK cell-mediated tumor rejection, this protein arises as a highly-targeted component of the degranulation pathway." (PMID 32466293, 2020). "Granzyme A (GZMA) and perforin 1 (PRF1) secreted by cytotoxic T-cells and NK cells are able to kill tumor cells." (PMID 33254149, 2020). "Tumor cells have evolved distinct strategies to interfere with PRF1 and/or GZM function, thus leading to immune escape." (PMID 32466293, 2020). "PRF1 monomers are glycoproteins that, similarly to the complement membrane attack complex, aggregate and form a pore in the membrane of the tumor cell, hence allowing the internalization of GZMs into the cytosol and eliciting osmotic imbalance." (PMID 32466293, 2020). "Cytolytic activity score (CYT), defined as the sum of expression of granzyme A (GZMA) and perforin (PRF1), was used to evaluate overall anti-cancer immune cell killing in the tumor microenvironment (25594174)." (PMID 33371179, 2020). "Expression of IFNG, CD30, CXCL13, and PRF1 was associated with increased level of immune infiltrates (CD8+ T cells, dendritic cells, and neutrophils) within the tumor." (PMID 31998644, 2019). "An mRNA-based metric of immune cytolytic activity, defined as average expression of perforin 1 and granzyme A, was devised to quantify anti-tumor immunity." (PMID 30847026, 2019). "The loss of perforin expression was displayed to be originated from the level of PRF1 transcript in SN, which was also seen in tumor CD8+ T cells." (PMID 29966014, 2018). "CD8 T cells from P14 mice harboring a defective perforin gene were able to stop tumor formation after transduction of the PRF1 gene, with similar results in vitro." (PMID 29355678, 2018). "In the complete response (CR) cases, 999 overexpressed genes including at least 234 tumor-specific CTL-activation associated genes such as IFNG, PRF1, and GZMB, were found in post-treatment biopsy specimens." (PMID 26625258, 2015). "Interestingly, tumor cells of Prf1–/– mice exhibited reduced MHCI surface expression compared with those from Prf1+/+ mice." (PMID 40627458, 2025). "Moreover, the genes related to T cell activation, such as Pdcd1, Cxcr6, Gzma, Gzmb, and Prf1, also upregulated in the tumor of αmPD1-IL-2x and mAWT020 treated mice." (PMID 40046051, 2025). "Co-culture with Prf1-/- NK cells only led to a minor growth impairment of the tumour cells." (PMID 39642167, 2025). "The pore-forming protein perforin (PRF1) is a definite marker of the killing ability of immune cells and is involved in the establishment of immune homeostasis, elimination of pathogens, and tumor surveillance." (PMID 40761790, 2025). "PRF1 may therefore play a significant role in cancer prognosis depending on several factors, such as the type of tumor, its stage, the treatment regimen, and the patient’s overall health." (PMID 39199299, 2024). "Similarly, FGFBP2+ NK cells also highly expressed markers like GNLY, NKG7, and PRF1, indicating a strong anti-tumor immune response." (PMID 39093451, 2024). "In this study, we introduce the role of PRF1 in cancer by describing the biological functions of PRF1 in tumor cells, as well as the role of PRF1 in tumor immunity and the microenvironment, and the therapeutic role of PRF1 in tumors and the prognosis of PRF1 on tumors in these sections." (PMID 39199299, 2024). "Some cancer patients have low levels of PRF1 expression in their immune systems, which may contribute to tumor growth and spread." (PMID 39199299, 2024).
tumor (continued). "In conclusion, we found that PRF1 plays a very important role in a variety of cancers, and it is responsible for tumorigenesis, development, and metastasis, in addition to regulating cell cycle progression and modulating the tumor microenvironment." (PMID 39199299, 2024). "Perforin 1 (PRF1) is a protein secreted by cytotoxic T lymphocytes (CTLs) and natural killer (NK) cells, which plays a key role in the immune system’s ability to kill tumor cells." (PMID 39199299, 2024). "Studies suggest that PRF1 activity may be influenced by the tumor microenvironment, such as inhibitory cytokines produced by tumor cells." (PMID 39199299, 2024). "The results showed that PRF1 levels were elevated after treatment or in the response group, suggesting that PRF1 may play an essential role in tumor immunotherapy." (PMID 37291495, 2023). "Immune-related genes, such as CD8A, CD8B, GZMA, GZMB, and PRF1, that may indicate the function of tumor-infiltrating CD8 + T cells were considerably enriched in the group receiving combination therapy." (PMID 37777634, 2023). "To further reveal the mechanisms underlying the helper functions of NK cells in CD8+ T cell‐dependent anti‐PD‐L1 immunotherapy, we set out to determine tumor growth after anti‐PD‐L1 immunotherapy in mice with NK cell‐specific deletion of Prf1, Ifng, Tbx21, or Eomes." (PMID 36807566, 2023). "Data from spleen show similar trend to breast between the untreated tumour and treated tissue, however the exception is that with the exception for PRF1 all other genes show higher expression in the verteporfin-PDT with BCL3 and CXCL1 showing the highest similar to that seen in breast tissue." (PMID 38022682, 2023). "To gain additional insight into how CAR4 T cells contribute to tumor destruction, we performed intravital imaging of the bone marrow in mice with established pro-B-cell tumors and treated with WT or IFN-γ−/− or perforin-deficient (Prf1−/−) CAR4 T cells." (PMID 37248395, 2023). "PRF1 has been shown to play a role in allowing tumor cells to perforate and rupture the membrane, releasing more DAMPs and leading to more immune cells recognizing and engulfing tumor cells, an essential feature in activating complete adaptive immunity." (PMID 37291495, 2023). "However, anti-PD-L1 treatment resulted in upregulation or downregulation of numerous genes in CD45+ tumor-infiltrating immune cells in TCh3 tumors, including Cd3d, Cd3e, Cd3g, Cd8a, Cd8b1, Nkg7, Ccl5, Ets1, Icos, Cxcr6, Pdcd1, Lag3, Prf1, and Gzmb (right)." (PMID 35366939, 2022). "Among them, the expression levels of CD8A, CD8B, GZMA, GZMB, and PRF1 were used to evaluate the infiltration levels of tumor cytotoxic T lymphocytes (CTLs), and a high-CTL-infiltration group has been related to significantly prolonged survival time of patients receiving immunotherapy." (PMID 36405701, 2022). "These included key genes associated with cytotoxic anti-tumor T cell responses (GZMA, GZMB, PRF1), co-stimulation of T cells (CD27, CD28, ICOS), and genes associated with other immune processes, including Type I IFN response (TNF, TNFSF10), as well as T cell exhaustion (CTLA4)." (PMID 36698398, 2022). "Furthermore, the relationship between the expression of GZMA, PRF1 and tumor purity and immune cells was investigated, which indicated the similar findings." (PMID 35812403, 2022). "Furthermore, we found a strong correlation of TIL score with the expression of the cytolytic marker genes GZMA and PRF1 indicating an abundance of CTLs and NK cells in these tumor samples." (PMID 33980253, 2021). "CYT quantified the cytolytic activity of the local immune infiltrate based on transcript levels of two key cytolytic effectors, granzyme A (GZMA) and perforin (PRF1), which represented the process of killing cancer cells that tumor immunotherapy strategies aim to boost." (PMID 33915876, 2021).
tumor (continued). "The cytolytic protein perforin-1 was significantly increased by TILs from rSmeg-hMIF-hIL-7 compared with the TILs from Smeg, suggesting that TILs in response to rSmeg-hMIF-hIL-7 more effectively induced tumor cell death." (PMID 34389619, 2021). "Therefore, the CYT score based on GZMA and PRF1 expression levels is considered a rational method to reflect the activity of tumor‐infiltrating CD8+ T cells and the antitumor immune response." (PMID 33769705, 2021). "Similarly, within the CD8+ T cell compartment, those at the tumor were also more activated, expressing high levels of Ifng (interferon γ [IFNγ]), Prf1 (perforin), and Gzmb (granzyme B)." (PMID 32433953, 2020). "In addition, NK cells induce the expression of FasL/Fas (FAS/FASLG), leading to apoptosis of tumor cells, and also affect tumor cells via multiple approaches, including direct lysis by perforin 1 (PRF1) and granzyme A and B (GZMA and GZMB)." (PMID 33276627, 2020). "Besides, CD274, CD8A, GZMA, and PRF1 were positively correlated with the stromal score or immune score in almost all 33 tumor types." (PMID 33585244, 2020). "Moreover, GZMA and PRF1 also showed a tightly co-expressed correlation in 32 of the 33 tumor types (except for LAML), which is consistent with the previous study." (PMID 33585244, 2020). "However, PRF1 levels were also determined in PyMT tumor interstitial fluids of all treatment groups." (PMID 33014872, 2020). "In addition to activation of the death receptor pathway, exocytosis of cytotoxic granules with perforin (PRF1) and granzymes (GZMs) is a major mechanism of NK cell-induced apoptotic tumor cell death." (PMID 32466293, 2020). "PRF1 is essential for the NK cell control of tumor development and metastasis." (PMID 32466293, 2020). "The microarray data revealed 728 distinctly regulated genes between two populations and the top highly expressed genes (IL2RB, GZMA, GZMB, EMR4, PRF1, CX3CR1, STAT1, and TLR9) in lung-derived Ly6C+ cells from EMT6 tumor-bearing mice are associated with effector T-cell function." (PMID 30926774, 2019). "Analysis of the whole-tumor lysates from Camkk2−/− mice showed a remarkable upregulation of genes expressed in the cytotoxic effector lymphocyte subsets, such as Granzyme B (Gzmb) and Perforin-1 (Prf1) (top)." (PMID 31164648, 2019). "Indeed, we detected that CD8, GZMA and PRF1 transcription levels were drastically increased in post-treatment tumor tissues of patients who responded, suggesting an activated and expanded T cell repertoire." (PMID 29721177, 2018). "Direct sequencing of the coding region and flanking intronic sequences revealed no mutations in PRF1 or in the putative tumour suppressor UNC5B." (PMID 20140240, 2010). "In a 2004 Nature correspondence, Qin and Blankenstein provide evidence that is reminiscent of Stutman's work, demonstrating that the rate and frequency of 3-MCA-induced tumour formation is similar between RAG-1−/− or perforin-1−/− mice and immunocompetent mice." (PMID 19638986, 2009). "However, SnMP treatment in Prf1–/–MMTV-PyMT mice resulted in a cessation of tumor growth." (PMID 40627458, 2025). "Upon contact of CTL with tumor cells, the transmembrane region of PRF1 is responsible for inserting it into the cell membrane, while the N-terminal hydrophobic region is responsible for the formation of pores in the tumor cell membrane, leading to tumor cell lysis and death." (PMID 39199299, 2024). "Additionally, we performed correlation analysis to corroborate the relationship between tumor infiltrated immune cells and the expression of the seven key hub genes (CTLA4, PRF1, LCK, CD3E, CD247, ZAP70, and LCP2) in ARID1A-PIK3CA mutational co-occurrence tumors." (PMID 38017109, 2023). "Mice with NK cell activating factors, including IFNγ, perforin 1 (PRF1), or TRAIL deficiency by gene knockout or antibody-caused neutralization, were more susceptible to metastatic incidences following challenges with tumor cell inoculation or with carcinogen-induced tumors." (PMID 37190251, 2023).